TNF (tumor necrosis factor)
Diseases named in the same sentence as TNF in open-access papers (continued):
Sharing a sentence is not in itself a finding about the gene and the disease.
cardiovascular disease (continued). "In our study, the higher levels of TNF-α, IL-1β, and IL-6 in PBMCs from AP individuals were also accompanied by the upregulation of several cardiovascular disease biomarkers like adiponectin and angiogenin." (PMID 35300329, 2022). "TNF-α is also a proinflammatory cytokine with a wide range of biologic effects and is involved in the pathophysiology of various cardiovascular diseases." (PMID 35372585, 2022). "In particular, proinflammatory markers, such as TNF-α and iNOS, are upregulated in cardiovascular disease." (PMID 35678673, 2022). "Tumor necrosis factor (TNF-α), Interleukin (IL)-1, and IL-6 are the typical inflammatory cytokines that cause cardiovascular disease." (PMID 36547425, 2022). "Biologicals, such as anti-tumor necrosis factor (anti-TNF), reduce cardiovascular disease (CVD) in patients with inflammatory rheumatic diseases." (PMID 35962246, 2022). "With regard to cardiovascular disease (CVD), abatacept showed a lower risk of stroke, HF, and MACE than rituximab in patients with RA who had previously failed TNF inhibitors." (PMID 36430392, 2022). "Simultaneously, leptin can stimulate inflammatory responses and up-regulate pro-inflammatory elements such as TNF- and IL-6, hastening the onset and progression of cardiovascular disease." (PMID 36186974, 2022). "In another Swedish regional register, the incidence rate of the first cardiovascular disease event was lower in anti-TNF-treated patients (14.0/1000 person-years) than in those who were not treated (35.4/1000 person-years)." (PMID 35844550, 2022). "TNFα signalling and its role in the progression of cardiovascular disease has been studied extensively however animal studies have found conflicting effects of TNFα inhibition (reviewed in Rolski and Błyszczuk, 2020)." (PMID 36339576, 2022). "As inflammation was shown to play a critical role in cardiovascular disease, the pro-inflammatory cytokine TNF-α was highlighted as a potent therapeutic target for cardiovascular disease." (PMID 34071276, 2021). "AF can stimulate the release of pro-inflammatory cytokines and chemokines related to cardiovascular disease and tissue injuries such as angiotensin II, interleukin (IL)-6, IL-8, and tumor necrosis factor (TNF)-α." (PMID 34781940, 2021). "Further, apabetalone diminished the production of pro-inflammatory cytokines (TNF-α and IL-1β) in hyper-responsive monocytes isolated from diabetic patients with cardiovascular disease." (PMID 33919584, 2021). "Studies have shown that main neuroactive cytokines involved in hypothalamic inflammatory mechanisms related to cardiovascular diseases are TNF-α, IL-6, IL1-α/IL-1β, and IL-10." (PMID 33967677, 2021). "These electrochemical biosensors for non-invasive detection of TNF-α cytokines have promising prospects for continuous, fast, real-time, and portable monitoring of cardiovascular disease." (PMID 34621727, 2021). "In a cross-sectional study, a significantly reduction of circulating serum TNF-α, which is a predictive factor of cardiovascular diseases, was observed among participants over the course of a smoking cessation program." (PMID 33995400, 2021). "Due to phosphorylation of NF-kB, AngII signaling directly influences the levels of inflammatory cytokines such as tumor necrosis factor alpha (TNFα) or interleukin 1 beta (IL1ß), which are drivers of chronic inflammation in cardiovascular diseases." (PMID 33807982, 2021). "Nonetheless, the pro-inflammatory cytokines such as TNF-α and IL-6, are responsible for the development and progression of cardiovascular diseases." (PMID 34073506, 2021). "More notably, the serum of cardiovascular disease patients contains a large quantity of inflammatory mediators, including interleukin-6 (IL-6), interleukin-1β (IL-1β), C-reactive protein, and tumor necrosis factor-α (TNF-α)." (PMID 34830730, 2021).
cardiovascular disease (continued). "The inflammatory response of cortisol is congruent to the fact that cardiovascular diseases are often related with proinflammatory cytokines such as IL-1, IL-6, and TNF-α." (PMID 33466883, 2021). "IL-6 and TNF-α are fundamentally acknowledged as inflammatory indicators in rats suffering from cardiovascular disorders." (PMID 34526481, 2021). "The pathogenic activity of proinflammatory cytokine tumor necrosis factor-α (TNF-α) promotes inflammatory response and plays a pivotal role in the progression of in atherosclerostic cardiovascular diseases." (PMID 34976297, 2021). "In particular, a chronic increase of plasma levels of pro-inflammatory cytokines such as interleukins IL-6, IL-1β, IL-17, and TNF-α is known to characterize cardiovascular diseases including IHD." (PMID 34112104, 2021). "Increased expression of TNF-α is observed in autoimmunological diseases, carcinogenesis, cardiovascular system diseases, or nervous system diseases." (PMID 34640602, 2021). "Oral glucose tolerance tests (OGTT) were performed, the cardiovascular disease (CVD) risk estimated, and TNF-α, an inflammatory cytokine, measured." (PMID 32599711, 2020). "The release of TNF-α and IL-17, pro-inflammatory cytokines and mediators of cardiovascular diseases, was evaluated after experimental envenomation with Aah venom in the presence or absence of the selective ETA-R antagonist, BQ123." (PMID 32545475, 2020). "Currently, data points to interleukins and TNF-α as cytokines that, at least in some settings, are effective targets to reduce cardiovascular disease progression." (PMID 32941503, 2020). "Upregulation of major cardiovascular disease related proinflammatory cytokines, TNF-α, IL-1β and IL-6, were inhibited with anti-LOX-1 receptor antibody treatment." (PMID 32182251, 2020). "Controlled TNF-α expression can convey tissue repair and cardioprotection; however, sustained expression is connected to detrimental outcome in cardiovascular diseases." (PMID 32708790, 2020). "TNF-α has been connected to pro-osteogenic pathways in in vitro cultures of VICs; the role of TNF-α in cardiovascular disease is, however, contradictory." (PMID 32708790, 2020). "Summary of phenotypes observed in animal models of cardiovascular diseases in relation to modification of the TNF-α signaling pathway." (PMID 33053859, 2020). "Adipokines, primarily adiponectin and TNF-α, secreted by fat tissue, also contribute to endothelial damage, which is regarded as the initiation of cardiovascular diseases." (PMID 32194402, 2020). "During cardiovascular disease, TNF-α can quickly enhance the endothelial cell adhesion factors, expand the accumulation of the inflammatory cells, activate the endothelial cells and finally start the secretion of inflammatory mediators into the serum." (PMID 32762480, 2020). "Among these inflammatory markers, TNF-α was particularly interesting for its role in cardiovascular diseases." (PMID 29487525, 2018). "The stimulatory chain from TNF-α and IL-1b to R/C can also have a pathogenomic effect in cardiovascular diseases." (PMID 30174768, 2018). "Increasing evidence has demonstrated that TNF-α reduces endothelium viability and promotes its apoptosis, which contributes to the development of cardiovascular diseases." (PMID 29805311, 2018). "Addition of SPC to VSMC induced also the release of TNF-α, an inflammatory cytokine involved in cardiovascular disease." (PMID 26466367, 2015). "Treatments that significantly modulated TNF‐α secretion were further explored for their effect on IL‐1β, as with TNF‐α, IL‐1β is a critical mediator in inflammation where blockade inhibits the progression of cardiovascular disease." (PMID 25801720, 2015). "For example, interferon-γ triggers formation and release of ROS in cardiovascular disease and tumor necrosis factor-α increases ROS generation in the rat myocardium." (PMID 25599803, 2015).
cardiovascular disease (continued). "There is evidence, in advanced cardiovascular disease patients, that cEPCs are reduced potentially due to the myelosuppressive effects of TNF-α." (PMID 26044827, 2015). "We examined relationships of leptin, resistin, TNF-α, and adiponectin with RV morphology and function (from cardiac MRI) in participants (n = 1,267) free of clinical cardiovascular disease from the Multi-Ethnic Study of Atherosclerosis (MESA)-RV study." (PMID 26348768, 2015). "In the present study, to increase the potential for using andrographolide to treat cardiovascular diseases, we showed that andrographolide inhibits TNF-α-induced iNOS expression in rat VSMCs." (PMID 25114952, 2014). "Taken together, these findings suggest that iNKT cells from HIV-infected patients with concurrent bone and cardiovascular disease selectively produce high levels of TNF, both constitutively and upon stimulation." (PMID 25329381, 2014). "Although clinical studies are still lacking, the available experimental literature provides some clues on the plausible mechanisms linking obestatin and obestatin-TNF-α interactions with cardiovascular diseases." (PMID 24102059, 2013). "In addition to modifying IL-1α, IL-1β, IL-6, TNF-α, and IL-17A levels, five nights of sleep restriction are accompanied by increased heart rate; both proinflammatory cytokines and hypertension are important risk factors for development of cardiovascular disease." (PMID 24367384, 2013). "Furthermore, increased TNFα levels have been shown to be increased in diseases associated with COPD such as cardiovascular disease and as such, systemic treatment with low dose Cyclosporin A and prednisolone may result in improvements of a broad range of inflammatory conditions associated with COPD." (PMID 23731729, 2013). "The proinflammatory cytokines such as tumor necrosis factor alpha and interleukin-6, involved in the pathogenesis of RA, are also independently predictive of subsequent cardiovascular disease (CVD)." (PMID 23024462, 2012). "This study provides a mechanistic framework for developing food-derived peptides as next-generation TNF-alpha antagonists and supports United Nations SDGs 3 and 9 by promoting innovative, low-toxicity therapeutics for chronic inflammation and cardiovascular diseases." (PMID 41341997, 2025). "MIAT is closely related to cardiovascular disease and is involved in the NF-κB pathway, promoting the expression of pro-inflammatory cytokines like IL-6 and TNF-α, and influencing the osteogenic differentiation of human adipose-derived and bone marrow mesenchymal stem cells." (PMID 39898106, 2025). "Thus, it is collectively obvious that DEX-induced IR in rats is associated with cardiovascular disorders in the aorta through modulation of oxidative/inflammatory pathways by elevating the JNK, NF-κB, TNF-α, ET-1, VCAM, and eNOS/PGI2 pathways." (PMID 40406487, 2025). "Further research into selective TNF-α inhibitors and their impact on cardiovascular hemodynamics may hold the key to novel treatments for cardiovascular disorders." (PMID 39519510, 2024). "At the same time, another meta-analysis of randomized clinical trials aimed to determine the effect of statins on serum levels of TNF-α, MCP-1, VCAM1 and IL-6 in patients with cardiovascular diseases showed that statins have a beneficial effect on reducing the serum levels of TNF-α." (PMID 38572445, 2024). "In fact, previous research has confirmed that EAT participates in the occurrence and progression of cardiovascular diseases by synthesizing and secreting proinflammatory mediators and neurohormones such as IL-1β, IL-6, TNF-α, MCP-1, resistin, visfatin, and others." (PMID 38277087, 2024). "TNF-α and IL-6 are key inflammatory factors in cardiovascular diseases." (PMID 39275259, 2024).
cardiovascular disease (continued). "Nevertheless, there is preliminary evidence suggesting a possible association between positive psychological processes (e.g., positive affect, gratitude) and lower levels of inflammatory markers (e.g., TNF-α, interleukin-6, C-reactive protein) in individuals with cardiovascular disease." (PMID 37213708, 2023). "Genus Bifidobacterium has been demonstrated to improve intestinal barrier function and modulate the secretion of proinflammatory cytokines (such as TNF-α), which may improve cardiovascular diseases." (PMID 37762194, 2023). "In addition, cytokines such as TNF, which are increased at inflammatory sites, directly activate platelets, further promoting the development of thrombosis and cardiovascular diseases with enhanced inflammation." (PMID 37109382, 2023). "The TNF-α expression was higher in obese patients with cardiovascular disease (CAD)." (PMID 37179331, 2023). "As IL-6 and TNF-α play a role in cardiovascular disease pathogenesis, they might be useful as therapeutic targets." (PMID 37887854, 2023). "However, the experimental and clinical studies concerning the possible interrelationships among TNF cytokines (such as TNF-a), inflammageing and cardiovascular diseases are less numerous compared to other cytokines." (PMID 36614282, 2023). "Moreover, elevated serum levels of TNF-α, IL-6 and CRP have been shown to increase the risk of cardiovascular diseases." (PMID 36434695, 2022). "It is accepted that cardiovascular disease is a competing risk in AKI/CKD and share common pathophysiological pathways such as TNF-α/TNFR and therefore, underlying inflammation and kidney tubule injury may represent a separate pathway." (PMID 36567329, 2022). "• RS supplementation reduced the inflammatory marker TNF-α and heart rate, but it did not significantly improve glycemic control and other cardiovascular disease risk factors among pre-diabetic adults." (PMID 35096939, 2021). "Evidence indicates that the effect of EAT on cardiovascular disease may mainly result from its release of endocrine proinflammatory mediators such as interleukin-6 (IL-6) and TNF-α." (PMID 33978815, 2021). "The anti-inflammatory effects of Magliocco are probably ascribable to its quite high content of epicatechin, catechin, and flavanols that beneficially impact the endothelial function and prevent cardiovascular diseases by reducing the proinflammatory milieu in TNF-α-activated endothelial cells." (PMID 34073604, 2021). "Pro-inflammatory adipokines excreted by hypertrophic adipocytes, namely interleukin (IL)-1β, IL-6, nuclear factor kappa-light-chain-enhancer of activated B cells (NF-κB), and tumor necrosis factor (TNF)-α can exacerbate various metabolic and cardiovascular diseases." (PMID 34685001, 2021). "In the present study, we demonstrated the role of TIFA protein, a transducer that sustains the positive feedback signaling in the TNF-α–NF-κB axis, in the crosstalk between endothelial, smooth muscle, and immune cells following development of cardiovascular diseases in PAH20,26,27." (PMID 34238983, 2021). "More importantly, bazedoxifene protected VECs from TNF-α-induced damage, suggesting that bazedoxifene may play a protective role in cardiovascular diseases through regulating the complex network connecting CD40, STAT3, AKT, ERK, and NF-κB signaling." (PMID 33381228, 2020). "The primary adipokines that play a role in inflammation, metabolic and cardiovascular diseases include adiponectin, leptin, resistin, visfatin, tumor necrosis factor alpha (TNF-α), interleukin-6(IL-6), plasminogen activator inhibitor-1 (PAI-1), and vascular endothelial growth factor (VEGF)." (PMID 33050331, 2020). "Given the important role of TNF-α and fibrinogen for inflammation and coagulation cascade in cardiovascular disease, our results support that short-term PM exposure might cause adverse effects on the human body through inflammation and coagulation cascade." (PMID 33254709, 2020).
cardiovascular disease (continued). "Additionally, LncRNA RP5-833A20.1 has also been reported to elevate the levels of inflammatory factors, such as IL-1β, IL-6, and, TNF-α in THP-1 macrophages in cardiovascular disease." (PMID 32629426, 2020). "Moreover, reduction of TNF-α levels below baseline raises concern regarding its use as prophylactic or preventive adjunct therapy in cardiovascular disease." (PMID 30813472, 2019). "Concordantly, studies have shown the association of inflammatory markers especially CRP which is among the GPS score variables, interleukin-6 (IL-6), tumor necrosis factor alpha, pentraxin 3 and neutrophil-to-lymphocyte ratio with poor prognosis in cardiovascular diseases." (PMID 31096693, 2019). "There are data to suggest that biologic therapies, in particular TNFα antagonists, may improve surrogate markers of cardiovascular disease and reduce CV adverse outcome." (PMID 30619884, 2018). "TNF-α plays a critical role in vascular dysfunction in cardiovascular diseases, which may be exploited to treat inflammation in a clinical setting." (PMID 29348768, 2017). "TNF-α is the major inducer of endothelial cell death in cardiovascular diseases." (PMID 29069811, 2017). "Studies report that blood levels of TNF-α and oxidative stress are higher in diabetic subjects and are indicative of an ongoing inflammatory response that ultimately results in development of cardiovascular disease." (PMID 27687012, 2016). "Moreover, overexpression of HO-1 has been shown to inhibit up-regulation of proinflammatory adhesion molecules in tumor necrosis factor (TNF)-α-activated ECs and to have anti-inflammatory therapeutic potential in various cardiovascular disorders." (PMID 26690352, 2015). "Cytokines, TNF α, IL-6, JAK1 and STAT3 as markers of inflammation response may play a major role in the risk for cardiovascular disease, which is also recognized as essential mediator of pathological aging." (PMID 25524239, 2014). "Prior studies also found that IL-6, TNF-α, and CRP are associated with cardiovascular diseases." (PMID 27429271, 2014). "TNFα-induced apoptosis in ECs also contributes to the pathogenesis of many cardiovascular diseases." (PMID 24991819, 2014). "Within the limitations of this study, it may be concluded that the clinically successful non-surgical periodontal therapy tend to reduce concentration of circulating pro inflammatory cytokines (CRP, TNF-α), which could be important for cardiovascular disease." (PMID 24198887, 2013). "Although a number of studies have documented a lack of link between the TNF-α −863C>A polymorphism and cardiovascular disease, in the current study we have observed a strong association of the said polymorphism with CHD in a Pakistani population." (PMID 24381514, 2013). "Thus identification of the intermediary steps involved in the TNF-α induced cardiomyocyte apoptosis can offer potential therapeutic targets to abrogate TNF-α induced cardiovascular diseases." (PMID 21949832, 2011). "Increased expression of VCAM-1 and ICAM-1 has been shown in SLE tissues such as the skin and heart and high levels of VCAM-1, associated with enhanced systemic TNF-α activity, was recently demonstrated to characterize SLE patients with manifest cardiovascular disease." (PMID 19997561, 2009). "Among them, interleukin 6 (IL-6), tumor necrosis factor-α (TNF-α), and fibroblast growth factor 23 (FGF-23) are robust independent predictors of all-cause mortality in stage 5 CKD patients, with IL-6 also serving as a reliable classifier of clinically overt cardiovascular disease." (PMID 41295836, 2025). "The outcome measurements were cardiometabolic indices and risk factors for metabolic and cardiovascular diseases, including anthropometric index (body weight, BMI, WC), BP, lipid profile (TG, TC, HDL, LDL), glycemic markers (FBG, Hb1AC, Insulin), and inflammatory markers (CRP, IL-6, TNF-α)." (PMID 39285289, 2024).